PLEKHA5 (pleckstrin homology domain containing A5)
Synonyms: PEPP-2; KIAA1686; PEPP2; FLJ10667
Tractability: PROTAC: UniProt records ubiquitination sites on it; ubiquitination databases record sites on it; its protein half-life has been measured.
Gene: Protein-coding gene on chromosome 12 (19,129,524 to 19,376,403, forward strand). Ensembl gene ENSG00000052126.
Subcellular location: Cytoplasm
Subcellular location (Human Protein Atlas): Cytosol; Nucleoplasm
Pathways (Reactome):
Metabolism: Synthesis of PIPs at the plasma membrane
Gene Ontology:
Molecular function: protein binding; phosphatidylinositol-3,5-bisphosphate binding; phosphatidylinositol-3-phosphate binding; phosphatidylinositol-4-phosphate binding; phosphatidylinositol-5-phosphate binding
Cellular component: cytosol; membrane; cytoplasm; glutamatergic synapse; postsynaptic density
Genetic constraint (gnomAD): Loss-of-function variants: 13 observed, 56.08 expected, observed/expected ratio (o/e) 0.23, 90% interval 0.15 to 0.37. The upper end of that interval is the gene's LOEUF score, 0.37, which puts it in group 1 of 6, group 1 being the genes least tolerant of losing a copy. Missense variants: 644 observed, 705.83 expected, observed/expected ratio (o/e) 0.91, 90% interval 0.85 to 0.97. Synonymous variants: 262 observed, 256.54 expected, observed/expected ratio (o/e) 1.02, 90% interval 0.92 to 1.13.
Homologues: Orthologues: chimpanzee PLEKHA5 (99% identical), macaque PLEKHA5 (98% identical), dog PLEKHA5 (94% identical), rabbit PLEKHA5 (88% identical), rat Plekha5 (87% identical), pig PLEKHA5 (87% identical), guinea pig PLEKHA5 (87% identical), mouse Plekha5 (86% identical), tropical clawed frog plekha5 (56% identical), zebrafish plekha5 (50% identical). Paralogues in human: PLEKHA7 (31% identical), PLEKHA6 (24% identical), PLEKHA4 (15% identical).
Diseases named in the same sentence as PLEKHA5 in open-access papers:
PLEKHA5 is named in the same sentence as 27 diseases in open-access papers, as found by Europe PMC text mining. Sharing a sentence is not in itself a finding about the gene and the disease. The quoted sentences say what the papers report.
melanoma (11 papers, 2016 to 2025). A malignant, usually aggressive tumor composed of atypical, neoplastic melanocytes. "We utilized Transwell chamber migration assays to demonstrate that the elevated expression of PLEKHA5 in melanoma cells post-brain metastasis was associated with a marked enhancement in migratory capacity." (PMID 40356756, 2025). "For example, expression of NDRG1 (N-mycdownregulated gene 1) is higher in BrM-initiating breast tumour cells, and expressionof PLEKHA5 (Pleckstrin homology domain-containing A5) in melanoma is associatedwith brain-specific metastasis." (PMID 35225863, 2022). "High PLEKHA5 expression in melanoma patients was associated with decreased brain metastasis-free survival, which is defined as the elapsed time from diagnosis of first distant metastasis to the diagnosis of brain metastasis." (PMID 27598148, 2016). "In addition to melanoma, PLEKHA5 has also been associated with gastric cancer, with studies finding that tyrosine phosphorylation of PLEKHA5 is MET-dependent and associated with MET expression and phosphorylation." (PMID 38818040, 2024). "Additionally, the high expression of PLEKHA5 in melanoma was associated with poor prognosis." (PMID 40356756, 2025). "To further substantiate our findings, we conducted colony formation assays to evaluate the impact of PLEKHA5 on the anchorage-dependent growth and proliferative capacity of melanoma cells." (PMID 40356756, 2025). "The functional effect of PLEKHA5 isoforms (Long or Short) on proliferation and migration of melanoma was studied by RNA interference, overexpression by lentivirus vector, CCK8 test, colony formation test, transwell chamber assay." (PMID 40356756, 2025). "Collectively, these results suggest that downregulation of PLEKHA5 can inhibit the proliferation of melanoma cells." (PMID 40356756, 2025). "Collectively, our results indicate that PLEKHA5 is highly expressed in melanoma cells with a propensity for brain metastasis and plays a promotional role in the formation of melanoma brain metastases in mice." (PMID 40356756, 2025). "To confirm the role of PLEKHA5 on melanoma malignancy, we applied the in vitro assays on another melanoma cells A2058 that expressed more PLEKHA5 than M1 cells." (PMID 40356756, 2025). "Next, we examined the expression of PLEKHA5 in melanoma and compared the differences in PLEKHA5 expression between primary and brain metastatic groups." (PMID 40356756, 2025). "To investigate the role of PLEKHA5 in the regulation of melanoma brain metastasis, we initiated our study with a series of experiments to assess the proliferative capacity of melanoma cells." (PMID 40356756, 2025). "To explore the role of PLEKHA5 in the regulation of melanoma brain metastasis, we initiated our investigation with a series of left ventricular injections in mice." (PMID 40356756, 2025). "The transcriptional profiles of totaling 7 melanoma samples, including 4 primary and 3 brain metastatic tissues were studied on the single-cell RNA sequencing level, and the expression of PLEKHA5 was examined in tumor clusters." (PMID 40356756, 2025). "Utilizing the Transwell chamber migration assay, we observed a significant reduction in the number of A2058 cells traversing the Transwell chamber following PLEKHA5 knockdown, indicating that PLEKHA5 knockdown can inhibit the migration of melanoma cells A2058." (PMID 40356756, 2025). "We further investigated the impact of PLEKHA5 knockdown on the migratory capacity of melanoma cells." (PMID 40356756, 2025). "On conclusion, we analyzed the brain metastatic melanoma at single cell level and found PLEKHA5 expression was upregulated, which was subsequently validated in nude mice model." (PMID 40356756, 2025). "Previous reports have shown that PLEKHA5 is highly expressed in melanoma brain metastases and promotes the growth of melanoma brain metastases." (PMID 40356756, 2025).
melanoma (continued). "Subsequent investigations linked its expression to early-stage brain metastasis development, demonstrating that PLEKHA5 inhibition suppresses melanoma cell proliferation and invasion in both intracranial and extracranial microenvironments." (PMID 40356756, 2025). "In our previous study, downregulation of PLEKHA5 by shRNA sensitived melanoma cells to the AKT inhibitor." (PMID 40356756, 2025). "We found that PLEKHA5 was highly expressed in tumor cell cluster 0, 2, and 7, indicating that PLEKHA5 is upregulated in melanoma brain metastasis samples." (PMID 40356756, 2025). "To date, the most thoroughly studied aspect of PLEKHA5 has been its potential regulatory role in melanoma brain metastasis." (PMID 38818040, 2024). "Further studies are needed to define the interaction of PDCD4 and PLEKHA5 and to evaluate the utility of this pathway as a therapeutic target in melanoma brain metastasis." (PMID 33801444, 2021). "Our past studies suggest PDCD4 interacts with Pleckstrin Homology Domain Containing A5 (PLEKHA5) to influence melanoma brain metastasis outcomes, as high intracranial PDCD4 expression leads to improved survival." (PMID 33801444, 2021). "We previously established Pleckstrin Homology Domain Containing A5 (PLEKHA5), a gene involved in normal brain development, as a regulator of melanoma growth in brain metastasis." (PMID 33801444, 2021). "For example, KRAS (KRAS Proto-Oncogene, GTPase) is also located in the SSC5 interval containing PLEKHA5 and is an appealing candidate for melanoma development since RAS proteins frequently undergo somatic or even germline mutations in melanoma." (PMID 29963229, 2018). "Pleckstrin homology domain-containing family A member 5 (PLEKHA5) is a recently described candidate to emerge from integrated comparisons of clinical melanoma samples and cell lines with a “brain homing” phenotype." (PMID 27598148, 2016). "PLEKHA5 silencing decreased melanoma cell survival and inhibited transmigration through an in vitro BBB model, suggesting that PLEKHA5 plays a role in viability and extravasation into the brain parenchyma." (PMID 27598148, 2016). "In melanoma, PLEKHA5 was initially reported to be highly overexpressed compared to normal tissues." (PMID 40356756, 2025). "PLEKHA5 expression increased in brain metastatic melanoma at single cell level." (PMID 40356756, 2025). "However, it is currently unclear which form of PLEKHA5 plays a role in the formation of melanoma brain metastases." (PMID 40356756, 2025). "Although existing studies have established the pro-metastatic role of PLEKHA5 in melanoma brain metastasis, its precise biological functions and molecular mechanisms during this process remain unclear." (PMID 40356756, 2025). "Furthermore, silencing PLEKHA5 expression in an experiment in vitro decreased the transmigration and invasion of melanoma cells across the BBB." (PMID 37190188, 2023). "In melanoma cells, PLEKHA5 knockdown was reported to reduce RB phosphorylation." (PMID 33677467, 2021). "In contrast, Jilaveanu and colleagues showed that PLEKHA5 (also on SSC5) was involved in melanoma cells survival and “brain homing” of metastatic cells through extravasation, but the exact mechanisms remain unknown." (PMID 29963229, 2018). "It will be interesting to determine the mechanism by which PLEKHA5 mediates intracranial extravasation and whether it is important for melanoma brain metastasis formation in vivo." (PMID 27598148, 2016). "PLEKHA5 has also been reported to be involved in the central nervous system homing mechanism in metastatic disease, and inhibition of PLEKHA5 may reduce the passage across the blood-brain barrier and reduce the proliferation and survival of melanoma cells in the brain and extrabrain regions." (PMID 38818040, 2024).
melanoma (continued). "In our previous study of cerebrotropic melanomas, we found the mechanism accounting for PDCD4 loss or suppression was post-translational, via proteasomal degradation and likely regulated by the crosstalk of PLEKHA5, a mediator of brain metastasis, with the PI3K/AKT and ubiquitin-proteasome pathways." (PMID 33801444, 2021). "Published studies have indicated that PLEKHA5 plays different roles in breast cancer, melanoma, and gastric cancer, and the reasons for the functional differences of PLEKHA5 in different tumors are not yet clear." (PMID 40356756, 2025). "The third SSC5 region extended over 2 Mb (between 55 and 57 Mb), with the best SNP located within the PLEKHA5 (Pleckstrin Homology Domain Containing A5) gene (DRGA0005864, p-value = 1.99 × 10–5), recently described as a mediator of distant melanoma metastasis in the brain." (PMID 29963229, 2018). "A few genes located nearby the most significantly associated SNPs in this study have been described as involved in melanoma tumor biology (CKAP4, ID4, SATB1, and PLEKHA5), but not in melanoma susceptibility." (PMID 29963229, 2018).
gastric cancer (4 papers, 2021 to 2025). A primary or metastatic malignant neoplasm involving the stomach. "We first examined the expression and tyrosine phosphorylation of PLEKHA5 in a panel of gastric cancer cell lines." (PMID 33677467, 2021). "PLEKHA5 has been identified to regulate tumor growth in metastatic melanoma and gastric carcinoma." (PMID 36417130, 2023). "Met or PLEKHA5 silencing also blocked the growth of MKN45 cells but did not affect that of other gastric cancer cell lines, including KATO-III that has FGFR2 gene amplification, and normal mesothelial cell line without Met gene amplification." (PMID 33677467, 2021).
breast carcinoma (3 papers, 2020 to 2025). "To further investigate the metastatic function of mutated PLEKHA5 in human breast cancer, we knocked out PLEKHA5 in GFP-labeled BRCA1-WT MDA-MB-231 cells (231-GFP)." (PMID 32978388, 2020). "Intriguingly, a tendency for the co-occurrence of mutations in Arhgef11 and Plekha5 was observed in our single-cell data, as well as in analyzed human breast cancer data." (PMID 32978388, 2020). "In addition, we performed Plekha5 knockout in a GFP-labeled mouse Brca1-deficient mammary tumor cell line with low metastatic potential (G600-GFP) and implanted these cells into mice." (PMID 32978388, 2020). "Paradoxically, PLEKHA5 exhibits tumor-suppressive effects in breast cancer metastasis, with knockout models displaying enhanced migratory and invasive capacities." (PMID 40356756, 2025). "Collectively, all this evidence of PLEKH5 in human breast cancers is consistent with the data obtained from functional studies in mice, which suggests that PLEKHA5 is a tumor metastasis suppressor of breast cancer." (PMID 32978388, 2020). "Meanwhile, we also showed that Plekha5/PLEKHA5 deficiency does not affect tumor growth; thus, we intend to believe that Plekha5/PLEKHA5 is a metastasis suppressor in breast cancer, which subjects to further investigation." (PMID 32978388, 2020).
breast tumors (2 papers, 2020 to 2022). "To extend our findings to the human database, we analyzed PLEKHA5 expression in a collection of 155 breast tumors with or without metastasis." (PMID 32978388, 2020).
metastatic disease (2 papers, 2020 to 2024). "Notably, Plekha5 was also mutated in PT cells (153PT: 10/18, 55.5%) and most often mutated in metastatic tumor cells (153LMT: 17/20, 85%), as revealed by single-cell sequencing, but it failed to be detected in PT bulk sequencing." (PMID 32978388, 2020).
metastatic melanoma (2 papers, 2021 to 2023). A melanoma that has spread from its primary site to another anatomic site. "Our previously reported data on PLEKHA5 as a regulator of metastatic melanoma growth indicated an inverse relationship between PLEKHA5 and PDCD4." (PMID 33801444, 2021).
brain tumor (1 paper, 2018). "PLEKHA5 facilitates cell migration and invasion and is linked to brain tumor metastasis via the PI3K-AKT pathway, whereas ST3GAL5 encodes a sialyltransferase that catalyzes the formation of ganglioside GM3, a suppressor of EGFR/PI3K-AKT signaling and cell proliferation, and a inducer of apoptosis." (PMID 29587824, 2018).
diabetes (1 paper, 2018). "While many of these variants lack functional validation and were not reported in other studies, genetic alterations or expression changes of some of the corresponding genes are associated with diabetes-related glycemic traits (e.g., HbA1c levels for TMC8 and T1D-related seroconversion for PLEKHA5)." (PMID 30126146, 2018).
lung carcinoma (1 paper, 2021). "Similar to DGC cells, Met or PLEKHA5 knockdown significantly suppressed the growth of Met-addicted EBC-1 lung carcinoma cells." (PMID 33677467, 2021).
lung squamous cell carcinoma (1 paper, 2021). "PLEKHA5 was also tyrosine-phosphorylated in a Met activity-dependent manner in EBC-1 lung squamous cell carcinoma cells that have Met gene amplification and are addicted to Met signaling." (PMID 33677467, 2021).
Obesity (1 paper, 2018). Accumulation of substantial excess body fat. "Moreover, we observed candidate association of rs6271 in the DBH gene, rs62618693 in the QSER1 gene, and variants in PCDHA1, RAD51B, and PLEKHA5 with non-T2D-linked obesity." (PMID 30126146, 2018). "In our study, we observed several highly case-specific variants in genes previously not directly linked to T2D and/or obesity (e.g., TMC8, PCDHA1, PLEKHA5, HBQ1, VAV3, and ADAMTS13)." (PMID 30126146, 2018).
skin melanoma (1 paper, 2021). "This may explain why the The Cancer Genome Atlas skin melanoma fails to show a correlation between PDCD4 and PLEKHA5 mRNA levels." (PMID 33801444, 2021).
type 1 diabetes (1 paper, 2018). "Expression levels of another gene harboring association signal, PLEKHA5, are linked to seroconversion behind type 1 diabetes." (PMID 30126146, 2018).
Varicose veins (1 paper, 2024). Enlarged and tortuous veins. "A comprehensive analysis indicated that KRTAP5-AS1, PLEKHA5, CBWD1, and CRIM1 might be potential drug targets for varicose veins." (PMID 38818040, 2024).
tumor (9 papers, 2018 to 2025). "PLAC1 is associated with placental development, TCF7 is involved in T cell differentiation, and PLEKHA5 has been linked to the suppression of tumor metastasis." (PMID 40607388, 2025). "Upon this, we finally identify a tumor metastasis suppressor Plekha5, whose deficiency promotes cancer metastasis to the liver and/or lung." (PMID 32978388, 2020). "Plekha5 encodes a protein containing a PH domain, but the role of Plekha5 in tumor formation and metastasis remains elusive." (PMID 32978388, 2020). "Of note, 65% (13/20) of 153LMT cells and 44% (8/18) of 153PT cells contained both the Arhgef11 mutation and the Plekha5 mutation, highlighting the power of single-cell technology in predicting possible collaborative actions for tumor evolution and tumor metastasis." (PMID 32978388, 2020). "Subsequently, we analyzed the expression of PLEKHA5 in normal versus tumor samples across different cancer types in the TCGA database." (PMID 40356756, 2025). "We found that PLEKHA5 expression in tumor samples was higher than in normal samples in both matched TCGA normal data and matched TCGA normal and GTEx data." (PMID 40356756, 2025). "Similar oncogenic roles are observed in MET-amplified diffuse gastric cancer, where PLEKHA5 silencing inhibits the growth of MET inhibitor-resistant tumor cells." (PMID 40356756, 2025). "We do not have evidence that unequivocally supports a functional role for the FRS2 and PLEKHA5 fusion events, and further studies are warranted to determine their role in tumour progression." (PMID 39322633, 2024). "In vivo orthotopic implantation assays showed that knockout of Plekha5/PLEKHA5 in multiple cell lines promoted tumor cell metastasis to other distant organs, such as the lung and liver." (PMID 32978388, 2020). "One hypothesis is that PLEKHA5 splice isoforms (PLEKHA5-L and PLEKHA5-S) may have opposing functions in tumor formation and metastasis." (PMID 40356756, 2025). "However, the low sample size precludes any general conclusions about the aggressiveness of PLEKHA5-rearranged tumours at this stage." (PMID 39322633, 2024). "However, it is possible that PLEKHA5 has both tumor-promoting and suppressive functions, depending on the cell context and cancer types." (PMID 33677467, 2021). "In addition, PLEKHA5 knockdown markedly reduced the incidence of bloody ascites formation and tumor dissemination to the diaphragm and liver." (PMID 33677467, 2021). "Plekha5 is mutated in PT cells and LMT cells, suggesting its role in tumor metastasis." (PMID 32978388, 2020). "We demonstrate that tumors initiate from cells with random SNVs affecting driver genes in the premalignant stage and malignantly progress later via CNVs acquired in chromosome regions with many cancer driver genes, including Plekha5, which acts as a tumor metastasis suppressor." (PMID 32978388, 2020). "In cases with PLEKHA5 and FRS2 rearrangements that were multi-sampled, the respective fusions were present in all investigated tumour materials (core needle biopsy, resection specimen, recurrence and/or metastasis), except for Case 12 (FRS2::ADAM32)." (PMID 39322633, 2024). "Future studies will focus on the interaction of PLEKHA5 and PDCD4 and the critical role of PDCD4 on boosting anti-tumor responses and survival in brain metastases." (PMID 33801444, 2021). "Extensive search of the literature revealed a potential key role of genes at the identified porcine loci in tumor invasion (DST, PLEKHA5, CBY1, LIMK2 and ETV5) and immune response modulation (ETV5, HERC3 and DICER1) of the progression phenotypes." (PMID 29963229, 2018). "Among them, the top up-regulated genes in tumor cells were those related to cancer progression (eg, AREG, CCL3, PLEKHA5, VCAM1 and MCM7), which might be the targets of innovative treatments." (PMID 36417130, 2023).